VGLL3 (vestigial like family member 3)
Diseases named in the same sentence as VGLL3 in open-access papers (continued):
Sharing a sentence is not in itself a finding about the gene and the disease.
VGLL3 also shares sentences with these, for which no sentence is quoted: breast tumor (2 papers); rheumatoid arthritis (2); scleroderma (2); Sjögren’s syndrome (2); Anxiety (1); dilated cardiomyopathy (1); ependymoma (1); esophageal carcinoma (1); fibrosis (1); glioma (1); head and neck squamous cell carcinoma (1); heart failure (1); heart hypertrophy (1); infection (1); ischaemic cardiomyopathy (1); lung adenocarcinoma (1); lymphoma (1); movement disorder (1); myxofibrosarcoma (1); neurodegenerative disease (1); osteosarcoma (1); ovarian cancer (1); perineurioma (1); pilocytic astrocytoma (1); skin inflammation (1); virus infection (1).